CD276 (CD276 molecule)
Diseases named in the same sentence as CD276 in open-access papers (continued):
Sharing a sentence is not in itself a finding about the gene and the disease.
oral cancer (10 papers, 2017 to 2025). "The knockdown of CD276 inhibits tumor growth, as it was also found that CD276 in Ca9-22 oral cancer cells can better interact with DC-SIGN with terminal α-galactose and higher fucosylation." (PMID 36358792, 2022). "Abnormal glycosylation, mostly high rate of fucosylation in B7-H3 during oral cancer, may lead to DCs tolerance because membrane proteins like DC-specific ICAM-3-grabbing non-integrin (DC-SIGN) and Langerin of DCs have a better affinity with CD276." (PMID 37605389, 2024).
ovarian tumor (10 papers, 2015 to 2025). "Interestingly, while traditional organoids derived from the same MUC1 and CD276 positive ovarian tumor tissue showed little or no activation, PSO demonstrated a significant level of activation." (PMID 38162496, 2023).
head and neck cancer (9 papers, 2017 to 2025). A primary or metastatic malignant neoplasm affecting the head and neck. "In a meta‐analysis consisting eight data sets of head and neck cancer gene expression profiling, the mRNA level of CD276 was significantly increased in HNSCC compared with the control counterpart (P < 0.05)." (PMID 28401653, 2017). "In addition, there is evidence that intrinsic CD276 (B7-H3) is a critical factor in evading the immune response by tumor stem cells in head and neck carcinoma." (PMID 36901916, 2023).
mantle cell lymphoma (9 papers, 2016 to 2024). Mantle cell lymphoma is a rare form of malignant non-Hodgkin lymphoma affecting B lymphocytes in the lymph nodes in a region called the ``mantle zone''. "Similarly, in MCL Z138 and Maver mantle cell lymphoma cell lines, the silencing of CD276 induces an arrest in the G0/G1 phase, inhibiting tumor proliferation." (PMID 36358792, 2022). "In hematologic tumors, especially in acute monocytic leukemia and mantle cell lymphoma (MCL), CD276 induces cell-cycle arrest in the G0/G1 phase, and xenograft models show the potent inhibitory role of CD276 in tumor growth." (PMID 36358792, 2022).
metastatic tumors (9 papers, 2019 to 2025). "As in our cohort 83% of patients had liver involvement in metastatic disease, this could interfere with tumor specificity of the CD276+CECs, due to CD276 expression on liver endothelial cells." (PMID 31948091, 2020).
autoimmune disease (8 papers, 2015 to 2025). A disorder resulting from loss of function or tissue destruction of an organ or multiple organs, arising from humoral or cellular immune responses of the individual to their own tissue constituents. "Regarding B7‐H3 (CD276), its dual role as both a co‐stimulatory and co‐inhibitory molecule in autoimmune diseases adds complexity to understanding its function in pSS." (PMID 40844039, 2025). "While aberrant CD276 expression in autoimmune diseases and cancer has been widely studied, its role at the maternal–fetal interface and in pregnancy-related disorders is controversial." (PMID 37685876, 2023).
nasopharyngeal carcinoma (8 papers, 2021 to 2025). A carcinoma arising from the nasopharyngeal epithelium. "In addition, as an immune checkpoint molecule, the increased expression of CD276 was shown to be associated with the level of immune infiltration in nasopharyngeal carcinoma." (PMID 36717836, 2023). "The pro-oncogenic kinase PBK was also shown to promote MSL phosphorylation on CD276, and to activate CD276 transcription in nasopharyngeal carcinoma." (PMID 36717836, 2023). "Here we demonstrate that a pro-oncogenic kinase PBK, the expression of which is associated with immune infiltration in nasopharyngeal carcinoma (NPC), stimulates the expression of CD276 epigenetically." (PMID 33431797, 2021). "PDZ-binding kinase (PBK), whose expression is associated with immune infiltration in nasopharyngeal carcinoma (NPC), also plays an important role in CD276 expression regulation." (PMID 33842369, 2021). "In nasopharyngeal carcinoma, PBK-mediated phosphorylation of MSL1 enhances MSL complex occupancy at the CD276 promoter, driving transcriptional activation of CD276 and promoting immune evasion." (PMID 41409271, 2025). "In nasopharyngeal carcinoma, PBK-mediated phosphorylation of MSL1 enhances CD276 transcription and facilitate immune evasion, implicating the MSL complex in tumor-associated immune regulation." (PMID 41409271, 2025).
thyroid cancer (8 papers, 2021 to 2026). "CD276 has been found to have an upregulated expression at the protein and mRNA levels in different types of thyroid cancer, and its effect on thyroid carcinoma has also been researched recently." (PMID 36120433, 2022). "CD276 was overexpressed in advanced thyroid carcinoma such as ATC, which is consistent with our results; its high expression indicates a poor prognosis of different PTCs." (PMID 36120433, 2022). "Finally, another study used three epithelial tumour markers known to be overexpressed in thyroid cancer: B7H3/CD276, MUC1, and EpCAM." (PMID 41193833, 2025). "Especially CD276, POSTN, and IFNA1 may be considered as new potential biomarkers associated with the prognosis of thyroid cancer." (PMID 36120433, 2022). "Especially CD276, POSTN, and IFNA1 may be considered as new biomarkers associated with the prognosis of thyroid cancer." (PMID 36120433, 2022). "Using the TISIDB database, we demonstrated that ALDH1A1/A3/B1 had significant negative correlations with immune-stimulating genes, such as CD276, TMEM173, TNFSF9, CD70, TNFRSF25, and CD40 in thyroid cancer." (PMID 35280765, 2022). "Our analysis concludes that TIMP1, LOX, CD276, IFNA1, TLR2, and POSTN are identified as thyroid cancer biomarkers, which lead to the different clinical courses of a woman older than 55 years old with papillary thyroid cancer." (PMID 36120433, 2022).
bladder tumors (7 papers, 2018 to 2024). "The expression of CD276 in bladder tumor samples and metastases was explored by immunohistochemistry." (PMID 35563359, 2022). "When correlating the CD276 expression to the tumor stage, elevated expression was found in all bladder tumor stages from T2a to T4b when compared to the median expression score of normal appearing urothelial samples from the same patients." (PMID 33845814, 2021). "Significant overexpression of CD276 was also noted by immunohistochemistry in bladder tumors samples when compared to benign urothelium obtained from the same bladders." (PMID 33845814, 2021). "In this context, the objective of this study was to study the expression levels of CD276 on well-characterized human urothelial cancer cell lines and in tissue samples from bladder tumors as a function of the tumor staging." (PMID 33845814, 2021). "We noted considerable variations of CD276 expression in individual samples from all stages of bladder tumors." (PMID 33845814, 2021). "Therefore, additional studies need to determine the correlation between total protein expression in bladder tumor tissue in comparison to the CD276 density on tumor cell surfaces." (PMID 33845814, 2021). "Based on this finding we hypothesize that elevated expression of proteases by the bladder tumor cells may play a role in degradation of even little CD276 from the surface of the benign cells surrounding the actual tumor." (PMID 33845814, 2021).
endometrial cancer (7 papers, 2017 to 2025). Primary or metastatic malignant neoplasm involving the endometrium (mucous membrane that lines the endometrial cavity). "CD276 expression in endometrial cancer is associated with higher tumor grade, shorter overall survival (OS) and less tumor infiltrating lymphocytes." (PMID 40707958, 2025). "Based on these data, we reasoned that targeting CD276 to improve its influx into the tumor site and achieve subsequent tumor cell killing in endometrial cancer with CC-3 would constitute a promising approach." (PMID 40707958, 2025). "We characterized CD276 surface expression on different endometrial cancer cell lines." (PMID 40707958, 2025). "We found that CD276 was highly expressed in three endometrial cancer cell lines." (PMID 40707958, 2025). "To address this medical need, and as TCGA data indicated high expression of the target antigen CD276 on tumor cells, we here evaluated the efficacy of our bsAb CC-3 targeting CD276 and CD3 as treatment option for endometrial cancer." (PMID 40707958, 2025).
mesothelioma (7 papers, 2018 to 2025). A usually malignant and aggressive neoplasm of the mesothelium which is often associated with exposure to asbestos. "B7-H3: B7H3 (also known as CD276) is another candidate checkpoint, whose expression has been observed in mesothelioma." (PMID 33952230, 2021).
metastatic prostate carcinoma (7 papers, 2021 to 2025). A carcinoma that arises from the prostate gland and has spread to other anatomic sites. "B7-H3(CD276), PSMA(FOLH1) and STEAP1 are co-expressed in metastatic prostate cancers." (PMID 40964329, 2025).
Wilms tumor (7 papers, 2008 to 2024). An embryonal neoplasm characterized by the presence of epithelial, mesenchymal, and blastema components. "Finally, the results showed that there were significant differences in CD80, CD48, IDO2, CD276, CD28, and CD200R1 between both groups, which could be used as potential therapeutic targets for the treatment of nephroblastoma." (PMID 38526609, 2024).
cutaneous melanoma (6 papers, 2018 to 2024). A primary melanoma arising from atypical melanocytes in the skin. "In the study of CD276 in cutaneous melanoma, researchers found that MiR-29c expression could inversely regulate CD276 expression." (PMID 33842369, 2021). "NKG2A is, contrary to primary NK cells, one of the few inhibitory receptors expressed by CD276-CAR NK-92 cells and their respective tumor cell ligands, HLA-E and HLA-G, are commonly overexpressed in cutaneous melanoma." (PMID 33925968, 2021).
experimental autoimmune encephalomyelitis (6 papers, 2013 to 2026). An autoimmune demyelinating disease of the central nervous system that is produced experimentally in animals by the injection of homogenized brain or spinal cord in Freund's adjuvant. "CD276 knockout mice showed higher differentiation of Th1-induced in response to more severe airway inflammation, more rapid development of experimental autoimmune encephalomyelitis, and higher autoantibody concentrations." (PMID 37685876, 2023).
lung squamous cell carcinoma (6 papers, 2015 to 2025). "Similar trends but less pronounced without reaching statistical significance were observed in lung squamous cell carcinoma, where the survival curves for high and low CD276 expression levels were more closely aligned." (PMID 40821788, 2025).
malignant glioma (6 papers, 2015 to 2025). A grade III or grade IV glioma arising from the central nervous system. "In addition, a comprehensive AI-guided correlation between CD276 expression and diagnostic features of malignant glioma, e.g., the different types of necrosis, should be feasible." (PMID 35884502, 2022). "In the case of CD276 when used as a marker of GSCs in malignant glioma, the method allowed us to predict system outcome on the basis of the graphs and attention scores that were generated." (PMID 38398141, 2024). "Our abGCN captures a distinct property of the CD276 high-expressing (CD276high) malignant glioma cell population (GSCs) in each slide in the form of graphs that are representative of the respective biopsy/case and based on global information from the WSI." (PMID 38398141, 2024).
prostate adenocarcinoma (6 papers, 2021 to 2026). "To assess the impact of ADT on B7-H3 expression in hormone-naive prostate adenocarcinoma, we first analyzed CD276 (B7-H3) mRNA expression level using high-risk PCa clinical cohort with 45 samples from radical prostatectomy." (PMID 37452083, 2023).
Sepsis (6 papers, 2016 to 2025). Sepsis is defined as life-threatening organ dysfunction caused by a dysregulated host response to infection. "In the high-risk group, LAIR1 was also elevated, as were immunosuppressive genes CD276, ICOSLG, and PDCD1LG2, which is consistent with immunosuppressive status in sepsis patients and further indicates that poor prognosis in patients with sepsis may be closely linked to immunosuppression." (PMID 40504881, 2025).
colon adenocarcinoma (5 papers, 2021 to 2026). "CD276 expression was significantly elevated in colon adenocarcinoma tumor (p < 0.0001)." (PMID 41725032, 2026). "In this study, we collected a dataset of colon adenocarcinoma (COAD) patients with H&E staining and transcriptome sequencing including CD276 from the Cancer Genome Atlas (TCGA) database." (PMID 38260829, 2023).
urothelial carcinoma (5 papers, 2021 to 2025). A malignant neoplasm derived from the transitional epithelium of the urinary tract (urinary bladder, ureter, urethra, or renal pelvis). "Our analysis highlighted a more pronounced expression of CD276 in high-grade urothelial carcinoma, thereby upholding the established link between elevated CD276 levels and this aggressive cancer variant." (PMID 39319055, 2024). "Elevated CD276 expression by urothelial carcinoma is associated with poor prognosis, but little is known about its expression across different tumor stages." (PMID 33845814, 2021). "Specifically, high-grade urothelial carcinoma showed elevated CD276 expression, reinforcing the connection between high CD276 levels and more aggressive cancer grades (p<0.05)." (PMID 39319055, 2024). "Examining the pathological grades, we discovered a pronounced elevation of CD276 in high-grade urothelial carcinoma compared to its lower expression in its low-grade counterparts, with this variation being statistically significant (p<0.001)." (PMID 39319055, 2024). "Nevertheless, enhanced levels of CD276 were more evident in older patients, those with high-grade urothelial carcinoma, and individuals exhibiting lymph node or distant metastases during advanced stages of the disease (p<0.05)." (PMID 39319055, 2024). "CD276 expression is significantly elevated in urothelial carcinoma cells in all stages but varies between individuals considerably." (PMID 33845814, 2021). "The urothelial carcinoma cell lines expressed significantly higher levels of CD276 on transcript (p < 0.006), total protein levels (p < 0.005), and on the cell surface (p < 0.02) when compared to normal urothelial cells." (PMID 33845814, 2021).
acute monocytic leukemia (4 papers, 2016 to 2022). Acute monoblastic leukemia (AML-M5), is one of the most common subtypes of acute myeloid leukemia (AML) that is either comprised of more than 80% of monoblasts (AML-M5a) or 30-80% monoblasts with (pro)monocytic differentiation (AML-M5b). "In the U937 acute monocytic leukemia cell line, the knockdown of CD276 is related to the decrease in PCNA and Ki67, inducing cell-cycle arrest in the G0/G1 phase, with a mean tumor growth rate of just 59.4% in xenograft models compared to the control group." (PMID 36358792, 2022).
adrenocortical carcinoma (4 papers, 2020 to 2023). "Based on two large, independent ACC cohorts, we performed the first study exploring the link between the differential expression patterns of CD276 and the clinical characteristics of adrenocortical carcinoma patients." (PMID 31998416, 2020). "Adrenocortical carcinoma (ACC) is characterized as a malignant adrenal tumor with a high recurrence rate and a short disease-free survival, and 91.7% (44/48) of ACCs expressed cytoplasmic and membranous CD276 in neoplastic or tumor associated vascular cells." (PMID 33842369, 2021).
papillary thyroid carcinoma (4 papers, 2022 to 2025). "TIMP1, LOX, CD276, IFNA1, TLR2, and POSTN have different expressions in PTCs, which lead to the various clinical courses of a woman older than 55 years old with papillary thyroid cancer." (PMID 36120433, 2022). "According to the ROC results, TIMP1, LOX, CD276, IFNA1, TLR2, and POSTN were considered to play a more critical role in malignant papillary thyroid cancer or immature cancer of papillary thyroid cancer." (PMID 36120433, 2022).
metastatic colorectal cancer (3 papers, 2020 to 2025). "We evaluated whether CD276+CEC is a clinically relevant biomarker to predict response to palliative systemic therapy in patients with metastatic colorectal cancer (mCRC)." (PMID 31948091, 2020).
Mycoplasma pneumoniae pneumonia (3 papers, 2016 to 2021). Interstitial pneumonia caused by extensive infection of the lungs (lung) and bronchi, particularly the lower lobes of the lungs, by mycoplasma pneumoniae in humans. "Studies have found that CD276 is associated with Mycoplasma pneumoniae pneumonia." (PMID 34917619, 2021).
neuroectodermal tumors (3 papers, 2021 to 2023). "B7-H3, also known as CD276, has been found to be highly expressed in most neuroectodermal tumors." (PMID 36765560, 2023).
bladder urothelial carcinoma (2 papers, 2024). "Another promising predictor biomarker of neoadjuvant chemotherapy response is B7‐H3 (CD276), an immune checkpoint molecule overexpressed in many cancers, including urothelial carcinoma of the bladder." (PMID 39539559, 2024). "In this study, we thoroughly examined CD276 expression to investigate its association with the prognosis and immune infiltration in BLCA, providing novel insights into potential diagnostic and therapeutic strategies for bladder urothelial carcinoma." (PMID 39319055, 2024).
gynecological cancers (2 papers, 2023 to 2024). "We also detected relevant surface biomarkers of these gynecological cancers, such as MSLN, MUC1, and CD276, in the PSOs and respective tumor tissues obtained from the same clinical samples." (PMID 38162496, 2023).
Hypertension (2 papers, 2020 to 2024). The presence of chronic increased pressure in the systemic arterial system. "Closer evaluation of six patients with baseline (CD276+)CEC values > mean +2 SD, revealed no hypertension or a history of peripheral vascular or cerebrovascular disease in these patients." (PMID 31948091, 2020).
invasive carcinoma (2 papers, 2020 to 2024). A carcinoma that is not confined to the epithelium, and has spread to the surrounding stroma. "CD276 cKI mice developed invasive carcinoma, whereas no invasive carcinoma was observed in control or CD276 cKI mice treated with R428." (PMID 38561369, 2024).
liver disease (2 papers, 2012 to 2020). "Since patients had to had adequate liver function to be eligible for study participation, important underlying liver disease interfering with CD276+CEC counts seems unlikely." (PMID 31948091, 2020). "Genes of inflammation and immunity (CD276, CDH6, GCKR, HNF1A, HPR, ITGA1, RORA, and STAT4) have been shown to be expressed in liver disease patients." (PMID 22530132, 2012).
metastatic cancer (2 papers, 2022 to 2023). A carcinoma which has spread from the original site of growth to another anatomic site. "In addition, another study found that compared with localized cancer, high expression of CD276 was more frequently observed in metastatic cancer and associated with high disease-specific mortality." (PMID 37179366, 2023).
Adrenal Tumors (1 paper, 2021). "CD276 expression in tumor blood vessels was significantly positively correlated with local invasion (higher T stage) and with advanced ENSAT stage (European Network for the Study of Adrenal Tumors)." (PMID 33842369, 2021).
atherosclerosis (1 paper, 2024). A disease characterized by the build-up of fatty material and calcium deposition in the arterial wall resulting in partial or complete occlusion of the arterial lumen. "The gene list included well-known atherosclerosis-associated genes Serpina3,42Cemip,43Thbs1,44Lum,45 and Spp146,47 but also novel genes without previous association to SMC function in atherosclerosis, such as Anxa4, Cd276, Itih4, Myof, Pcdh11x, Rab31, Serpinb6b, Slc35e4, Slc8a3, and Spink5." (PMID 38289873, 2024). "Moreover, we identified several novel genes not previously linked to SMCs in atherosclerosis, such as Anxa4, Cd276, inter-alpha-trypsin inhibitor-4 (Itih4), Myof, Pcdh11x, Rab31, Serpinb6b, Slc35e4, Slc8a3, and Spink5." (PMID 38289873, 2024).